CPSF6 (cleavage and polyadenylation specific factor 6)
Diseases named in the same sentence as CPSF6 in open-access papers (continued):
Sharing a sentence is not in itself a finding about the gene and the disease.
infection (continued). "An artificial construct composed of rhesus tripartite motif-containing (TRIM) 5 ring, B-box 2, and coiled-coil elements fused to CPSF6-358 similarly restricted infection by HIV-1 and SIVmac without perturbing MLV, EIAV, FIV, or bovine immunodeficiency virus (BIV) infection." (PMID 32994325, 2020). "We curated 46 CPSF6(+) RIGs from multiple cell types (HEK293T, HOS, MDM, and CD4+ T cells) and 30 CPSF6(−) RIGs from these same cells when infection occurred in the absence of the CA–CPSF6 interaction (i.e., N74D or A77V CA mutant viruses, or WT CA infection of CKO cells)." (PMID 32665593, 2020). "In contrast, infection of the N74D virus was not affected by CPSF6-358." (PMID 31511380, 2019). "We found that CPSF6 blocks CA mutants that are impaired for infection of non-dividing cells." (PMID 24415937, 2014). "As CPSF6 also binds the wild type HIV-1 capsid but does not inhibit infection by the wild type virus, it is possible that the RKLM substitutions weaken the interaction of the viral capsid with the nuclear pore, rendering the capsid sensitive to masking by CPSF6." (PMID 24415937, 2014). "Likewise, at 48 h post-infection (p.i.)under physiological infection conditions without drug treatment, vRNA foci could be detected inside CPSF6 clusters in most of the cells." (PMID 36314049, 2023). "Also CPSF6-358 did not significantly restrict FIV infection." (PMID 32994325, 2020). "It should also be considered that HIV-1 RTC/PIC arrested at or close to the nuclear pore in the absence of sufficient CPSF6 recruitment may eventually integrate into chromosomal DNA even without release from the nuclear basket, thus contributing to the observed infection rate." (PMID 30672737, 2019). "However, expression levels of CPSF6 in permissive and non-permissive cell lines were similar in our study, thus variations in its expression do not correlate with the cell-dependence of infection by the HIV-1-A92E mutant." (PMID 24663101, 2014). "Cells expressing the CPSF6-Rac3 NLS were less supportive of both HIV-2 and SIVmac expression, and SIVmac infection did not exhibit the same increase in infectivity as observed with HIV-1 and HIV-2 following infection of CPSF6-C-Myc NLS expressing cells." (PMID 39823525, 2025). "Protein lysates collected after interferon pre-treatment, but prior to infection, showed decreased levels of representative ISGs IFIT1 and MX1 upon CPSF6 knock-out, though not to the same extent as observed upon IFNAR1 knock-out." (PMID 41385587, 2025). "Protein lysates collected after interferon pre-treatment, but prior to infection, showed decreased levels of a representative ISG, MX1, upon CPSF6 knock-out, though not to the same extent as observed upon IFNAR1 knock-out." (PMID 39678349, 2024). "Consistent with previous studies, CPSF6-KO did not perturb HIV-1 infectivity in HeLa cells, and expression of CSPF6–358 in CPSF6-KO cells potently inhibited infection." (PMID 38979149, 2024). "Expression of CPSF6 lacking its nuclear localisation sequence (CPSF6ΔNLS) blocks reverse transcription, as does PF74, while BI-2 inhibits infection post-reverse transcription." (PMID 25356722, 2014). "However, infection of mutant HIV-1 viruses bearing the capsid changes N74D or A77V, which do not induce the formation of CPSF6 condensates during infection, were affected only ~ twofold." (PMID 37414787, 2023). "Although capsids bearing the N74D change do not interact with CPSF6, the infectivity defect that HIV-1-N74D viruses exhibit is due to a decrease in Cyp A binding with a concomitant gain of TRIM5αhu binding, which restricts infection." (PMID 35215956, 2022). "While not targets of clinical infection, HEK293T and Jurkat T cells were nevertheless chosen due to accessibility of complementary datasets derived from LEDGF/p75- and CPSF6-depleted cells, or from cells infected with CA mutant viruses that are defective for CPSF6 binding." (PMID 35203306, 2022).
infection (continued). "CPSF6-358 restricted infection by different primate lentiviruses including HIV-1, HIV-2, and simian immunodeficiency viruses derived from rhesus macaques (SIVmac and SIVmne) but not infection by the felid lentivirus feline immunodeficiency virus (FIV) or MLV." (PMID 32994325, 2020). "Furthermore, infection of CPSF6 knockout cells by HIV-1 results in an integration pattern similar to the integration pattern observed for HIV-1-N74D viruses; these results imply that in the absence of CPSF6 expression, HIV-1 wild type virus behaves like HIV-1-N74D viruses." (PMID 37414787, 2023).
cancer (27 papers, 2007 to 2025). A tumor composed of atypical neoplastic, often pleomorphic cells that invade other tissues. "Dysregulation of CPSF6 has been linked to cancer cell proliferation and metastasis." (PMID 40544380, 2025). "Notably, other groups have reported that CPSF6 relocalization to puncta within the nucleus is associated with preferential 3’ UTR lengthening in several cancer cell lines, pointing to other as-of-yet unexplored cell type differences that may influence CPSF6-mediated transcriptional reprogramming." (PMID 41385587, 2025). "Since c-Myc is involved in glycolysis 44 and cancer metabolism 45, the effect of CPSF6 on the metabolism of Hep3B cells was examined." (PMID 38993554, 2024). "The authors showed that in cancer cells, although overall CPSF6 levels were higher, the CPSF6 underwent less liquid-liquid phase separation (LLPS), resulting in fewer CPSF6 puncta." (PMID 38793552, 2024). "Collectively, our results are the first to demonstrate that CPSF6 functions as an oncoprotein by regulating cancer-related pathways in LUAD." (PMID 36446361, 2022). "It is very interesting that cancer is associated with global 3′UTR shortening relative to normal cells, and our results seem that CPSF6 promotes cancer via 3′UTR lengthening." (PMID 34594359, 2021). "To further examine the levels of CPSF6 in distinct GC stages and nodal metastasis, we evaluated the expression of CPSF6 in normal and GC tissues based on individual cancer stages or nodal metastasis." (PMID 34594359, 2021). "Importantly, CPSF6 has been found to promote cancer progression, while its depletion decreases cancer progression, dysregulates mRNA processing, and enhances antiviral immune responses." (PMID 41463412, 2025). "In addition to regulating the antiviral immune responses and orchestrating virus integration, CPSF6 is also involved in cancer progression and immunosuppression." (PMID 38416782, 2024). "However, the expression profile and biological function of CPSF6 on other types of cancer still needs to be addressed." (PMID 36446361, 2022). "Further IPA pathway analyses indicated that multiple cancer-associated pathways, such as transforming growth factor-β (TGF-β), mTOR, IGF-1, nuclear factor-κB (NF-κB) and phosphatase and tensin homolog (PTEN) pathways, were correlated with CPSF6 expression." (PMID 36446361, 2022). "We analyzed the differentially expression status of CPSF6 between normal tissue and tumor tissue in pan-cancer is retrieved from TIMER database, we found that CPSF6 is significantly higher expressed in tumor tissues than normal tissues in multiple cancer types, especially in both LUAD and LUSC." (PMID 36446361, 2022). "Finally, based on the bioinformatics results and subsequent verification data, the correlation between CPSF6 and cancer-related genes were established by IPA." (PMID 36446361, 2022). "We assumed that although CPSF6 could promote cancer via 3′UTR lengthening, the other APA factors still regulated 3′UTR shortening in GC cells and led GC cells to still prefer to use short 3′UTR." (PMID 34594359, 2021). "Furthermore, CPSF5 and CPSF6 are downregulated in cancers and their knockdowns in cell lines enhances oncogenicity." (PMID 31911652, 2020). "Furthermore, associations between MAP3K11, MTCH2 and CPSF6 to cancer have also not been previously reported." (PMID 18636107, 2008). "Cleavage and polyadenylation factor-6 (CPSF6), as one of the cleavage factor Im (CFIm) subunits during alternative polyadenylation (APA) of mRNA, has been thought to be related to the occurrence and development of cancer in recent years." (PMID 34217312, 2021). "We functionally confirmed this association in siRNA knockdown experiments of five PGC genes (p53CSV, MAP3K11, MTCH2, CPSF6, and SKIP), which either directly enhanced the invasive capacities or inhibited the proliferation of AGS cancer cells." (PMID 18636107, 2008). "CPSF6, for instance, is the second most amplified CPA gene in cancer." (PMID 41463412, 2025).
cancer (continued). "Here, we found that CPSF6 is significantly higher expressed in tumor tissues than normal tissues in multiple cancer types." (PMID 36446361, 2022). "To test this hypothesis, we first analyzed the mRNA expression of CPSF6 in GEO NSCLC datasets and revealed that CPSF6 levels were significantly elevated in NSCLC cancer tissues in comparison with normal lung tissues." (PMID 36446361, 2022). "Interestingly, the expression of miR-377, which often functions as a tumour suppressor, is downregulated in multiple cancer types, further suggesting a significant negative correlation between miR-377 and CPSF6 expression." (PMID 38416782, 2024). "An outstanding question is how the presence of CPSF6 puncta in cells for more than two weeks affects the polyadenylation of cellular mRNAs and whether this alters the function of infected MDMs, particularly as altered CPSF6 LLPS affected polyadenylation in cancer cells." (PMID 38793552, 2024).
tumor (10 papers, 2004 to 2024). "The higher CPSF6 expression was observed to be associated with tumor size (p < 0.001), advanced tumor-node metastasis (TNM) stage (p < 0.001), venous invasion (p < 0.001) and distant metastasis (p < 0.001) of the HCC patients." (PMID 33648552, 2021). "Although CPSF6 was reported to be involved in tumor progression in cancer, the underlying mechanisms are yet to be completely characterized." (PMID 33648552, 2021). "We also analyzed The Cancer Genome Atlas (TCGA) data from the TIMER database and found that CPSF6 is significantly high expressed in multiple tumour tissues than in normal tissues." (PMID 38416782, 2024). "Consistently, immunohistochemistry showed that CPSF6 depletion reduced the growth of Hep3B cells in BALB/c mice in orthotopic and xenograft tumor models by inhibiting tumor microenvironment-associated proteins." (PMID 38993554, 2024). "In this study, we first analyzed the CPSF6 levels using IHC assay in GC tissues and the paired non-tumor tissues." (PMID 34594359, 2021). "We next examined the protein expression of CPSF6 in non-tumor liver cell line HL-7702 and human HCC cell lines (Huh-7, HepG2, SK-HEP-1, PLC/PRF/5 and Hep3B)." (PMID 33648552, 2021). "We observed a significant increase in both tumor growth and weight; whereas a significant reduction in both tumor growth and weight was observed in CPSF6 knockdown tumors." (PMID 33648552, 2021). "CPSF6 staining was scored as a strong or moderate expression in 31 and 55% of tumor tissues, as compared with 9 and 33% in corresponding adjacent non-tumor liver tissues." (PMID 33648552, 2021). "To explore the clinical relevance of CPSF6 in GC patients, we next compared the expression of CPSF6 mRNA, with the RNA-seq data derived from GC (n = 352) and non-tumor tissues (n = 32) in TCGA." (PMID 34594359, 2021). "The elevated expression of CPSF6 was also observed in 33 out of 36 HCC tissues by western blot assay when compared with the adjacent non-tumor counterparts." (PMID 33648552, 2021). "Given that the metabolic product lactate is involved in the immune escape of tumor cells in the tumor microenvironment 37, we can expect that CPSF6 may regulate genes related to immune escape." (PMID 38993554, 2024). "Thus, in addition to its regulatory role in the proliferation, tumorigenicity, and cell death of tumour cells, the role of immunosuppression induced by high expression of CPSF6 in tumour progression should also attract more attentions." (PMID 38416782, 2024). "Furthermore, immunohistochemistry showed that the expression of CD4/CD8 was significantly increased in the tumor tissues of CPSF6 depleted Hep3B cells inoculated in BALB/c mice compared to that in the untreated control." (PMID 38993554, 2024). "Similarly, in an orthotopic tumor model, by direct injection of Hep3B cells into the livers of Balb/c nude mice, CPSF6 depletion significantly reduced the volumes of Hep3B cells and liver weights compared to the sham control group." (PMID 38993554, 2024). "In addition, the m6A readers, including YTHDF1/2/3, HNRNPC, HNRNPA2B1, RBMX, PRRC2A, and CPSF6, also demonstrated a higher expression in the tumor samples compared to the normal tissues." (PMID 38610981, 2024). "Given that CPSF6 involves in APA formation and its relevance in GC cells we hypothesized that CPSF6 acts as a tumor promoter in GC, at least in part, by influencing APA and 3′UTR." (PMID 34594359, 2021). "Furthermore, we demonstrated CPSF6 negatively regulated von Hippel Lindau (VHL), the gene encoding a tumor suppressor, through selective poly(A) usage, thus contributing to tumor growth in GC." (PMID 34594359, 2021). "We found CPSF6 promoted tumor growth and inhibited apoptosis in GC." (PMID 34594359, 2021). "VHL was demonstrated to contribute to the function of CPSF6-mediated tumor growth in GC cells." (PMID 34594359, 2021).
tumor (continued). "Thus, in the present study, the oncogenic mechanism of CPSF6 was elucidated in HCC tissues, cell lines, and orthotopic and xenograft tumor models in association with the Warburg effect, which is closely associated with angiogenesis and immune escape in the TME." (PMID 38993554, 2024). "In this study, the oncogenic mechanism of CPSF6 was explored in HCC tissues, cell lines, and xenograft and orthotopic tumor models." (PMID 38993554, 2024). "In a xenograft tumor model, the growth of Hep3B cells implanted into the right flank of BALB/c nude mice was significantly suppressed in the CPSF6 LV-shRNA-treated Hep3B group compared to that in the LV-shControl group." (PMID 38993554, 2024). "CPSF6 is able to upregulate NQO1 to regulate HCC cell metabolism and thereby promote tumor development." (PMID 36211823, 2022). "IHC staining assay showed that CPSF6 was upregulated in tumor tissues when compared with the surrounding non-tumor counterparts." (PMID 34594359, 2021). "Given that CPSF6 involves in APA formation and its role in promoting cell growth and restraining apoptosis in GC cells we hypothesized that CPSF6 acts as a tumor promoter in GC, at least in part, by influencing APA and 3′UTR." (PMID 34594359, 2021).
CPSF6 also shares sentences with these, for which no sentence is quoted: esophageal squamous cell carcinoma (5 papers); glioblastoma (3); myeloproliferative neoplasm (2); AIDS (1); Anxiety (1); asthma (1); co-infection (1); esophageal cancer (1); helminthic infections (1); immune diseases (1); immune thrombocytopenia (1); myeloid leukemia (1); ovarian carcinoma (1); psoriasis (1); rheumatoid arthritis (1); Sepsis (1); systemic lupus erythematosus (1); urothelial carcinoma of the bladder (1).